BRCA1 (BRCA1 DNA repair associated)
Diseases named in the same sentence as BRCA1 in open-access papers (continued):
Sharing a sentence is not in itself a finding about the gene and the disease.
breast cancer (continued). "They conducted scRNA-seq on breast cancer tissues and adjacent or prophylactic normal breast tissues from four BRCA1 mutation carriers." (PMID 34815798, 2021). "Inherited mutations in BRCA1 increase the risk of developing breast cancers by up to 72% and ovarian cancers by up to 69%, when compared to individuals with wild-type BRCA1." (PMID 35008272, 2021). "Prophylactic mastectomy is one of the most effective ways to prevent breast cancer development in carriers of BRCA1/2 mutations." (PMID 35008272, 2021). "An example of this is the FDA approved application of PARP inhibitors to treat breast cancer patients with a BRCA1 or BRCA2 mutation." (PMID 34615983, 2021). "In this prospective study of 1084 European women, we evaluated the impact of arsenic exposure on individuals who have inherited susceptibility to breast cancer because of mutations in the BRCA1 gene." (PMID 34283078, 2021). "The findings of this study therefore suggest a molecular basis for the combinatory effect of high MD and BRCA1/2 mutation on breast cancer risk reported by others." (PMID 34209669, 2021). "BRCA1 (FANCS) mutation carriers who unfortunately go on develop breast cancer mostly develop tumours which are HR−28, presumably due to inefficient DNA damage repair, which is also in line with this model." (PMID 34880407, 2021). "Similar to hereditary OC, most current evidence-based strategies for managing patients with known inherited risks of breast cancer (e.g. germline BRCA1/2 variants) rely on prophylactic surgeries such as bilateral mastectomies." (PMID 34064977, 2021). "Nonetheless, the prognostic significance of BRCA1/2 mutational status on breast cancer survival is still debatable." (PMID 34206661, 2021). "If the probability of having breast cancer given that the patient has a mutated BRCA1 gene were lower, then even if the patient has breast cancer, this information cannot be used to explain it." (PMID 34966640, 2021). "Accordingly, PARP inhibition is currently considered a targeted therapy for BRCA1-associated breast cancer." (PMID 33767581, 2021). "In most other breast cancer genes, including BRCA1 and BRCA2, it is the loss of DNA repair capacity that associates with variant severity." (PMID 34584094, 2021). "Knockdown of REV1 expression using miR-96 contributed to cisplatin sensitization in bone osteosarcoma cells with intact HR repair, as well as in BRCA1-deficient breast cancer and BRCA2-deficient ovarian cancer cell lines with compromised HR pathways." (PMID 35198436, 2021). "Recently, BRCA1:c.5470_5477del was also revealed as a founder mutation in a cohort of 9505 Han breast cancer patients, which made our conclusion more solid." (PMID 34046351, 2021). "In the present study, we determined and compared the EMT phenotype in mammary tumors developed in mice deficient for Brca1 or Gata3 under the same p18 deficient background." (PMID 34373738, 2021). "There were expected breast cancer associations with BRCA1 grade-3 ER− HER2−, significantly more frequent than high-risk BRCA-negative group (p < 0.0001)." (PMID 34312777, 2021). "P-RPS6 has been reported to confer the BRCA1-deficient breast cancer HCC1937 cells with resistance to the PARPi olaparib." (PMID 35008473, 2021). "Carriers with pathogenic variants in BRCA1 or BRCA2 were also more likely to have a family history of breast cancer than carriers of pathogenic variants in the other genes (p < 0.0001)." (PMID 34887416, 2021). "The so-called “Angelina’s effect” has impacted public’s health awareness of hereditary breast cancer and increased rates of genetic counseling and tests for BRCA1/2 mutations." (PMID 34285295, 2021). "We also explored the mechanisms underpinning high cyclin E1 expression in BRCA1 mutated breast cancer including gene amplification and protein stability." (PMID 34465787, 2021).
breast cancer (continued). "Couch and colleagues reported the association of the minor allele of MDM4 SNP rs2290854 with breast cancer risk in mutant BRCA1 carriers, suggesting that this MDM4 variant can be a modifying factor for breast cancer in this mutant background." (PMID 34307167, 2021). "Nonetheless, the efficacy of PARPi has been demonstrated amongst breast cancer patients with somatic mutations in BRCA1/2, including a cohort of 16 metastatic patients, where an ORR of 50% was observed (90% CI, 28% to 72%)." (PMID 34959671, 2021). "In a Japanese case series, two in five primary breast cancers in patients with BRCA1/2 mutation were only detectable on MRI in a 48-month breast cancer surveillance program including biannual ultrasonography, annual mammography, and MRI." (PMID 34336698, 2021). "Double heterozygotes were more likely to be diagnosed with breast cancer compared to women with only one deleterious BRCA pathogenic variant (68.1% vs. 52.0% for BRCA1, p = 0.002; 67.4% vs. 50.4% for BRCA2, p = 0.002)." (PMID 33507482, 2021). "So far, known genetic risk factors account for only 50% of the breast cancer genetic component and almost a quarter of hereditary cases are carriers of pathogenic mutations in BRCA1/2 genes." (PMID 33503040, 2021). "Taken together, these results suggest that co-treatment with irradiation and a PARP inhibitor facilitates growth-suppression and degeneration of BRCA1-associated mammary tumors." (PMID 33767581, 2021). "Women who carry inherited pathogenic mutations in the BRCA1 or BRCA2 genes possess an increased risk of developing breast cancer (BC) and ovarian cancer (OC) compared to women of the general population without these mutations." (PMID 34090422, 2021). "Meanwhile, more details are still badly lacking to figure out the origin and evolution of the heterogeneity among and within BRCA1-deficient mammary tumors." (PMID 34815798, 2021). "BRCA1-associated breast cancer is an extensively studied hereditary cancer that exhibits significantly greater genetic instability than sporadic breast cancers 34,35." (PMID 33767581, 2021). "BRCA1 promoter hypermethylation, as an inactivator of epigenetic modifications, was associated with a gene expression profile similar to that of inherited BRCA1 mutation-associated breast cancer." (PMID 34465315, 2021). "Only a small fraction of hereditary breast and/or ovarian cancer (HBOC) cases are caused by germline variants in the high-penetrance breast cancer 1 and 2 genes (BRCA1 and BRCA2)." (PMID 33498765, 2021). "For example, the NPP 2014‒2018, based on the public health genomics approach, aimed to develop organized paths of breast cancer prevention in women with BRCA1/2 mutations." (PMID 33669364, 2021). "Olaparib is used in the clinic for the breast cancer patients with mutated BRCA1 and/or BRCA2 where the HR DNA repair is impaired." (PMID 34572735, 2021). "We demonstrated that Gata3 deficient mammary tumors phenocopy Brca1 deficient tumors in induction of EMT, and that reconstitution of Gata3 in Brca1-deficient tumor cells activates MET suppressing tumor initiation and metastasis." (PMID 34373738, 2021). "Germline BRCA1/2 pathogenic variant (PV) carriers have high lifetime risk of developing breast cancer and therefore subjected to intense lifetime screening." (PMID 34540661, 2021). "This proof-of-concept phase II study with talazoparib as the single agent demonstrated activity in HER2-negative advanced breast cancer patients with an HR pathway mutation beyond BRCA1/2." (PMID 33800556, 2021). "In olaparib-resistant BRCA1-deficient breast cancer cells, ionizing radiation (IR) decreased the number of γ-H2AX foci and increased the number of DNA repair protein RAD51 homolog 1 (RAD51) foci compared with the numbers of them in the parental cells." (PMID 35008473, 2021).
breast cancer (continued). "It should also be noted that Beji and Reis analyzed the occurrence of breast cancer in the context of family history, writing that BRCA1/2 mutations are found in most families with a positive history of breast, ovarian, and endometrial cancer." (PMID 33925599, 2021). "Conversely, in BRCA1/2 mutation carriers, pre-menopausal obesity is associated with early-onset breast cancer." (PMID 33649363, 2021). "Here we present a clinical case of a 56-year-old female, a carrier of a mutation in the BRCA1 gene, with a history of breast cancer and with recurrent epithelial ovarian cancer." (PMID 33810213, 2021). "Of the known pathogenic variants related to hereditary breast cancer, those in the Breast Cancer Susceptibility Genes 1 and 2 (BRCA1/2) account for 50–60% of cases." (PMID 33507482, 2021). "The mean age at diagnosis of BRCA1/2-associated breast cancer is much lower and this cancer has biologically aggressive phenotypes." (PMID 34674065, 2021). "Improved predictors for identifying women and families who carry pathogenic variants in breast cancer predisposition genes other than BRCA1 and BRCA2 are urgently needed." (PMID 34887416, 2021). "Few published clinical studies have found that breast cancer patients with BRCA1/2 mutations show better prognosis than control groups, while others have reported that they have worse survival outcomes, whereas some studies reported similar prognosis." (PMID 34206661, 2021). "The mechanisms through which obesity contributes to early-onset breast cancer in BRCA1/2 mutation carriers are incompletely understood." (PMID 33649363, 2021). "Germline pathogenic variants in BRCA1 are found in about 7-10% of all familial breast cancers and 10% of ovarian cancers." (PMID 34828342, 2021). "Referral for the group of younger patients is important because young age at diagnosis of breast cancer indicates a higher risk to carry a BRCA1 or BRCA2 pathogenic variant and is a clear indication for referral to breast cancer genetic testing." (PMID 33933926, 2021). "Authors showed that estrogen activates the AKT pathway in BRCA1-deficient mammary tumors by enhancing the expression of p-Akt, p-mTOR, p-Gsk3 β, and p-4Ebp1, downstream targets of Akt." (PMID 33540843, 2021). "Other study showed that BRCA1-deficient breast cancer cells can transform CAFs to their altered activated phenotype, which the authors named metastasis associated fibroblasts (MAFs)." (PMID 33540843, 2021). "Secondly, it is important to note that only a subset (20–30%) of familial breast cancer is explained by a pathogenic variant in BRCA1/2 or another highly penetrant cancer gene." (PMID 34082720, 2021). "Of all breast cancer cases, 5–10% have a strong hereditary background and a recent study has estimated the prevalence of pathogenic variants in BRCA1 and BRCA2 among unselected breast cancer patients to be about 4.5%." (PMID 34529195, 2021). "Evidence on the prognostic relevance of BRCA1/2 mutations on breast cancer survival is still debatable." (PMID 34206661, 2021). "These are all low-risk susceptibility alleles identified through testing of candidates from breast cancer genome-wide association studies in BRCA1/2 mutation carriers and through fine-mapping of candidate regions." (PMID 34285278, 2021). "There are multiple pathogenic mutations in addition to BRCA1/2 that are implicated in causing hereditary breast cancer." (PMID 34046273, 2021). "Early clinical trials showed a lack of objective clinical responses in women with sporadic TNBC compared with those with BRCA1/2 mutated breasts cancers, who most benefited from this targeted therapy." (PMID 33470989, 2021). "For instance, BRCA1 is known to participate in the processes of DNA repairing, and its mutations/variants are known to have association with the onset of breast cancer and ovarian cancer." (PMID 33937409, 2021).
breast cancer (continued). "According to the results of an international BRCA1/2 cohort study, the cumulative risk of developing breast cancer among BRCA1/2 variant carriers reaches approximately 70% by the age of 80 (72% in BRCA1 variant carriers and 69% in BRCA2 variant carriers)." (PMID 35008774, 2021). "Olaparib is a newly approved poly (ADP-ribose) polymerase (PARP) inhibitor, indicated for the treatment of cancers that exhibit DNA repair defects, including BRCA1/2-mutated breast cancers." (PMID 33801148, 2021). "Subsequently, several studies in breast cancer patients found an association of BRCA1 expression levels and mutation status with the patient survival." (PMID 34966485, 2021). "We retrospectively reviewed ipsilateral breast cancer patients with BRCA1/2 mutation who underwent primary surgery between January 2008 and November 2019 at a single institution in Korea." (PMID 34285295, 2021). "Based on the results from cross-species comparison by unsupervised clustering, these tumors are closely similar to human BRCA1-mutated breast cancers with basal-like phenotypes." (PMID 33842308, 2021). "Since 19q12 (CCNE1) amplification is associated with poor survival in other cancer types we examined its relationship with overall survival in BRCA1 mutated breast cancer." (PMID 34465787, 2021). "In fact, of the 5–10% of breast cancer cases that are related to genetic mutations, 67% of those cases are due to BRCA1/2 mutations." (PMID 34711195, 2021). "The personal or family history of mammary malignancies and inherited genetic mutations in breast cancer susceptibility genes, mostly BRCA1 (BRCA1 DNA Repair Associated) and BRCA2 (BRCA2 DNA Repair Associated), account for 5% to 10% of breast tumor cases." (PMID 33498667, 2021). "To model human stromal cells with a heterozygous BRCA1 mutation, we used BRCA1-mutant human induced pluripotent stem cells (iPSCs) derived from the blood cells of patients with an inherited form of breast cancer." (PMID 33513753, 2021). "Women with a germline mutation in the tumor suppressor genes BRCA1/2 have a high lifetime risk of developing breast cancer (BC) or ovarian cancer (OC) (69–72% and 16–59%, respectively)." (PMID 34570303, 2021). "Accurate interpretation of BRCA1/2 variants is critical for risk assessment and precise treatment of breast cancer (BC)." (PMID 33461583, 2021). "We next examined the correlation between cyclin E protein alteration and BRCA1 by immunohistochemical staining of cyclin E in 21 breast cancer samples from patients who have germline mutations in BRCA1 treated at the MD Anderson Cancer Center." (PMID 33916118, 2021). "Overall findings indicate that increased EC risk for BRCA1/2 carriers has been associated with tamoxifen use for breast cancer prevention or treatment (since these genes confer high breast cancer risk) comparable to the risk observed in the general population." (PMID 33917078, 2021). "The greater risk of developing contralateral breast cancer in BRCA1/2 mutation carriers compared to women with sporadic cancer supports the necessity of RRM for the unaffected side of breast for BRCA1/2 mutation carriers." (PMID 34285295, 2021). "Due to a tight interconnection between BRCA1 and epigenetic mechanisms, BRCA1-deficient breast cancer cells are less sensitive to epigenetic inhibition, such as treatment with the HDAC inhibitor SAHA." (PMID 34638302, 2021). "Together, these data suggest that inhibition of PDGFR or PKCα activity efficiently kills BRCA1-deficient human breast cancer cells." (PMID 33478572, 2021). "We discovered that Gata3 deficiency activates EMT in the induction of mammary tumors and promotes tumor initiation as well as the metastatic potential of cancer cells, which phenocopy Brca1 deficient tumors and tumor cells." (PMID 34373738, 2021). "Annual breast-enhanced magnetic resonance imaging (MRI) is recommended for BRCA1/2 mutation carriers aged over 25 years as a secondary prevention of breast cancer." (PMID 34674065, 2021).
breast cancer (continued). "High mammographic density (MD) is a significant risk factor for the development of breast cancer, as is inheritance of mutations in BRCA1 or BRCA2 tumour suppressor genes." (PMID 34209669, 2021). "The EMBRACA trial focused on advanced breast cancer patients with a germline BRCA1/2 mutation, in which 431 patients were randomly assigned to receive talazoparib or standard therapy." (PMID 34448553, 2021). "Here, we examined the efficacy of radiotherapy, assessing the accumulation of genetic instabilities, in the treatment of BRCA1-associated breast cancer using a Brca1-mutant mouse model." (PMID 33767581, 2021). "The most important of these are the breast cancer susceptibility genes BRCA1 and BRCA2, and ATM and CHK2 are also important risk factors." (PMID 34198652, 2021). "A study including 1504 patients with germline BRCA1 or BRCA2 mutations showed that chemoprevention using tamoxifen is associated with a 50% reduction in the risk for developing contralateral breast cancer." (PMID 34206661, 2021). "Studies have shown that contralateral mastectomy in breast cancer patients with BRCA1/2 mutations can decrease breast cancer specific mortality." (PMID 34206661, 2021). "This was in line with the initial findings of Mitchell and colleagues, who also found a synergistic increase in breast cancer risk due to the combination of high MD and BRCA1/2 gene mutation carrier status." (PMID 34209669, 2021). "Her family history included one case of PC, one breast cancer and one endometrial cancer; her daughter, unaffected, carries the same BRCA1 mutation." (PMID 34034685, 2021). "As with cancers of the breast, ovary, and pancreas, germline mutations in BRCA1 and BRCA2 associate with an increased risk of developing PC, and approximately 5% of men with mPC carry inherited pathogenic mutations in these genes." (PMID 34877933, 2021). "The high-penetrant genes are, however, rare and although women with a BRCA1/2 mutation have a seven times higher risk of breast cancer, this subtype only explains up to 10% of all breast cancers." (PMID 34930164, 2021). "The mechanism(s) by which BRCA1-mutated stromal cells affect the pathogenesis of breast cancer remain to be clarified." (PMID 33513753, 2021). "Recently, we have reported a founder mutation, c.815_824dup, of the BRCA1 gene in Senegalese women with inherited breast cancer." (PMID 35096615, 2021). "Recently published guidelines offer recommendations on the management of breast cancer in patients with germline mutations in BRCA1/2, PALB2, CHEK2 and ATM." (PMID 34422626, 2021). "We also found that inhibition of PDGFR or PKCα activity efficiently killed BRCA1-deficient human breast cancer cells and that expression of BRCA1 was inversely related to that of PDGFRβ and PKCα in human breast cancer samples." (PMID 33478572, 2021). "Estimated cumulative risk for development of breast cancer in carriers of BRCA1 and BRCA2 mutation is 72% and 69%, respectively, up to the age of 80 years." (PMID 33540843, 2021). "Accordingly, a recent nested case-control study conducted in the USA revealed that only 1.18% of the unselected postmenopausal breast cancer patients were BRCA1/BRCA2 mutation carriers." (PMID 34287479, 2021). "We further checked the expression level of Mrc2 in the 4 subtypes of BRCA1-deficient mouse mammary tumors, and found Mrc2 was highly expressed in the mesenchymal-like tumors when compared to other 3 subtypes." (PMID 34815798, 2021). "Breast cancers with high levels of cyclin E not only have a higher prevalence of BRCA1/2 mutations, but also are associated with the worst outcomes." (PMID 33916118, 2021). "The lifetime risks for carriers of a BRCA1-pathogenic variant range from 65% to 79% for breast cancer and from 36% to 53% for ovarian cancer." (PMID 33921890, 2021). "In fact, 80% of women with a pathogenic mutation in BRCA1 who develop breast cancer have triple negative disease." (PMID 34711195, 2021).